MTOR (mechanistic target of rapamycin kinase)
Diseases named in the same sentence as MTOR in open-access papers (continued):
Sharing a sentence is not in itself a finding about the gene and the disease.
cancer (continued). "Activation of PI3K-Akt-mTOR is vital for cancer cell growth, survival, proliferation, migration, and metabolism, as well as angiogenesis and therapy-resistance." (PMID 33154352, 2020). "It proposed a useful mTOR-targeting therapeutic method for anti-GBM based on remodeling cancer metabolism and TIME." (PMID 32817393, 2020). "The BD has been demonstrated to exhibit anti-proliferative and pro-apoptotic effects against various cancer cell lines via inhibition of the key regulatory signaling pathways like PI3K/AKT/mTOR, JAK/STAT, JAG1/Notch." (PMID 36046775, 2020). "Increased activation of the phosphatidylinositol 3‐kinase (PI3K)/Akt/mechanistic target of rapamycin (mTOR) pathway leads to numerous hallmarks of cancer and this pathway represents an attractive target for novel anticancer therapies." (PMID 31989769, 2020). "The polypyrimidine stretch proximal to the 5′ end of these genes was a target for translation regulation, oxidative and metabolic stress, or cancer-induced differential translational regulation by the mTOR pathway." (PMID 33036380, 2020). "mTOR signaling is overactivated in many types of cancer including breast, ovarian, renal, colon, and head and neck cancers." (PMID 32012648, 2020). "Rapamycin is a known inhibitorof mTOR and has been tested clinically to treat cancer.On the other hand activating autophagy can induce cell death in target cancer cells and autophagy inhibitors have alsobeen tried clinically." (PMID 34621117, 2020). "Due to its central role in oncogenesis, mTOR has become a popular target for cancer therapy and a number of mTOR targeted therapeutics have been developed." (PMID 31974638, 2020). "It displays potent anticancer properties in different types of cancers, being able to suppress mammalian target of rapamycin (mTOR)." (PMID 32748870, 2020). "Over-activation of the Akt/mTOR signaling is involved in the elevated aerobic glycolysis of cancer cells, thereby contributing to cancer cell survival and growth." (PMID 32850379, 2020). "PI3K/AKT/mTOR inhibition via various molecules or compounds have been shown to induce cancer cell apoptosis through reduction of mitochondrial membrane potential, inactivation of XIAP, activation of caspase-3, upregulation of BAX and downregulation of Bcl-2." (PMID 32443471, 2020). "Drugs inhibiting the PI3K/Akt/mTOR pathway are reported to have promoting effects on apoptosis in cancer cells." (PMID 32340124, 2020). "Evidence has suggested that there is participation of ROS in controlling several autophagy regulating proteins, such as mTOR in cancer inhibition." (PMID 33053749, 2020). "LARP1 functions as a molecular switch for mTORC1-mediated translation of an essential class of mRNAs and posttranscriptionally regulates mTOR and contributes to cancer progression by regulating cell division, apoptosis, and cell migration." (PMID 33614632, 2020). "In response to targeted intervention, multiple mechanisms can converge on mTOR to rewire these processes, thereby promoting cancer cell survival and therapy resistance." (PMID 33318517, 2020). "Akt/mTOR signaling is closely linked to HIF-1α expression in the context of immunometabolic regulation during infection, and cancer-related aerobic glycolysis and tumor progression." (PMID 33262773, 2020). "Synergistic effects have been evoked on a panel of more than 60 human cancer cell lines treated with an mTOR-HDAC inhibitor combination, compared with single agent applications." (PMID 32512849, 2020). "The phosphoinositide 3-kinase (PI3K)/protein kinase B (AKT)/mammalian target of rapamycin (mTOR) signaling pathway participates in cell cycle regulation, and is directly related to cellular quiescence, proliferation, cancer, and longevity." (PMID 32751156, 2020). "Constitutive activation of the mTORC1, as one of the mTOR complexes, is identified in a few human cancers." (PMID 32899752, 2020).
cancer (continued). "Enrichment analysis indicated that cell cycle, DNA replication, pathways in cancer, mTOR signaling pathway, and VEGF signaling pathway were significantly enriched in the high CEP55 expression group." (PMID 32337246, 2020). "The range of cellular functions the mechanistic target of rapamycin (mTOR) protein performs makes it an attractive drug target for cancer therapy." (PMID 33142217, 2020). "Previous studies have focused on the crosstalk between SHH-GLI signaling and several oncogenic pathways including MAPKs, PI3K/AKT/mTOR, and TGFβ/SMAD signaling pathways, and implicated the strategy of targeting SHH-GLI and MEK1/2 for the therapy of cancers." (PMID 32670287, 2020). "Oncogenes highly expressed in cancer cells can activate the PI3K/AKT/mTOR signaling pathway to allow the related proteins such as ErbB2 and HIF-1 to promote the expression of lipid synthetases." (PMID 33194756, 2020). "In this study, we found that wild-type cancer cells die via apoptosis and necrosis, while drug-resistant cells survive through autophagy accompanied by mTOR activation." (PMID 32883024, 2020). "Direct pharmacologic inhibition of mTOR signaling is therefore an attractive therapeutic strategy for cancer treatment." (PMID 33144562, 2020). "While PI3K/Akt/mTOR pathway is activated in many types of cancer, little success has been achieved in cancer treatment by targeting the pathway, as tumours eventually evade repression of this pathway." (PMID 32463592, 2020). "The PI3K/AKT/mTOR signaling pathway not only plays a crucial role in physiologically cell biology, but also in cancer as it regulates cell proliferation, survival, migration, angiogenesis and the utilization of nutrition." (PMID 32962206, 2020). "This is one of the limited number of studies demonstrating the cancer radiosensitisation following isolated mTOR inhibition." (PMID 32443649, 2020). "Although the link between mTOR and Hh signalling was previously demonstrated in cancer development and progression, knowledge of their molecular crosstalk in healthy liver is lacking." (PMID 32751882, 2020). "The PI3K/AKT/mammalian target of rapamycin (mTOR) signaling pathway is typically abnormally activated in many carcinomas." (PMID 32626705, 2020). "Regarding the therapeutic effect of PF04691502 through inhibition PI3K/mTOR, clinical trials for some carcinomas were reported." (PMID 33005852, 2020). "Cancer cells in the face of acidic pH stimuli decrease mTORC1 activity and lose the anti-proliferative potential of mTOR inhibitors." (PMID 31557936, 2019). "The Akt/mTOR and the MAPKs signaling pathways can be concurrently constitutively activated in several human cancers and possible cross talks between these two cascades can drive tumor progression." (PMID 30813295, 2019). "AMPK negatively regulates the mTOR (mammalian target of rapamycin) signalling pathway, resulting in inhibition of cancer proliferation and growth." (PMID 30895533, 2019). "The mTOR pathway controls cell growth, metabolism, proliferation, angiogenesis, and survival (reviewed in reference 7) and is activated in a large number of cancers." (PMID 30782662, 2019). "Aberrant mechanistic target of rapamycin (mTOR) signaling has been observed in many types of human cancer." (PMID 31288154, 2019). "Induction the Akt/mTOR signaling pathway promotes radioresistance in various cancers, including NSCLC." (PMID 31613929, 2019). "Yet there are several reports which state that suppression of mTOR decreases activity of Aldh1 as well as EpCAM, the well-known markers for cancer stem cells." (PMID 31729456, 2019). "Promoter methylation‐mediated loss of SALL2 conferred an estrogen‐independent and tamoxifen‐resistant phenotype to ERα‐positive cancer cells via ERα downregulation and Akt/mTOR signaling activation." (PMID 31657150, 2019).
cancer (continued). "It is clear that the findings on the efficacy of ATP-competitive inhibitors of mTOR in clinical cancer therapy need more investigation." (PMID 31557936, 2019). "Dysregulation of cell cycle characterizes several types of tumors, and consequently, mTOR became an important therapeutic target for cancer patients." (PMID 30972289, 2019). "mTOR serves as the major growth and survival pathway for cancer pathogenesis and has been an attractive target development of anticancer therapies." (PMID 31075885, 2019). "For example, the prognostic impact of SOX9, SENP1 and mTOR was limited to ERG positive cancers while FOXA1, MTCO2 and FOXP2 were only prognostic in ERG negative cancers." (PMID 31606028, 2019). "EGFR and PTEN regulate the induction and progression of malignant tumors through the PI3K/mTOR signal transduction pathway." (PMID 30863440, 2019). "The anti-cancer effects of quercetin include its ability to promote the loss of cell viability, apoptosis and autophagy through the modulation of PI3K/Akt/mTOR, Wnt/β-catenin, and MAPK/ERK1/2 pathways." (PMID 31261749, 2019). "Further, in contrast to data found in cancer cells, mTOR activity was dispensable for MYC protein induction in naive and memory murine T cells, regulating PRMT5 expression via downregulation of Prmt5-targeting miRNAs or alternate mechanisms." (PMID 30941147, 2019). "The PI3K-Akt-mTOR pathway is upregulated in cancer cells, controlling the survival and proliferation of these cells." (PMID 30606113, 2019). "mTOR downstream from AKT controls NFκB activity in PTEN-null/inactive cancer cells via interaction with and stimulation of IKK." (PMID 31284467, 2019). "Under conditions of nutrient stress, autophagy functions via the mTOR pathway to promote metabolic homeostasis and survival of cancer cells." (PMID 31862913, 2019). "For example, mTOR inhibitors are in clinical trials for the treatment of various cancers but have thus far shown, in most cases, limited efficacy." (PMID 30967004, 2019). "Two murine studies suggested triple combination of external beam irradiation, PD-1 blockade, and CD137 agonism to synergize in cancer treatment, suggesting mechanistic target of rapamycin (mTOR) signaling to be involved in the therapeutic mechanism." (PMID 31905723, 2019). "Until recently, several inhibitors targeting mTOR had been studied for their efficacy in tumor therapy; among these, Torin 1 and Torin 2 are new generation mTOR inhibitors demonstrated to be effective in several cancer types." (PMID 31766386, 2019). "An increasing number of publications in recent years suggest that various NPs modulate mTOR activation, leading to cell cycle arrest in cancer cells." (PMID 30642006, 2019). "Through alterations in one or multiple of these elements, mTOR signaling is activated in many cancer types, suggesting mTOR as a potent target for cancer therapy." (PMID 30764584, 2019). "In cellular assays, B591 potently inhibited the dysfunctional activation of PI3K/mTOR pathway and attenuated the growth of a panel of cancer cell lines." (PMID 30635656, 2019). "In order to further determine the mechanism of QUE modulation of HK2 expression level, we focused on the Akt-mTOR pathway, which regulates a wide variety of cellular processes including cancer cells glucose metabolism." (PMID 31137633, 2019). "Focusing on muscle protein signalling, the mTOR pathway is an important pathway that is related to control of protein synthesis and is impacted by cancer cachexia." (PMID 31200474, 2019). "RES inhibits lipid synthesis via SREBPs inhibition, activates sirtuins concomitantly with the activation of AMPK, and downregulates the PI3K/AKT/mTOR pathway resulting in cancer cell apoptosis." (PMID 31159437, 2019). "The PI3K/PTEN/AKT/mechanistic target of rapamycin (mTOR) signal pathway has been clarified to be involved in the CXCR6/CXCL16 biological axis in the cancer realm." (PMID 30620718, 2019).
cancer (continued). "In summary, immune-related processes, mitochondrial dysfunction, and PI3K/AKT/MTOR signaling are biological processes that have been independently associated with both ASD and cancer." (PMID 31007884, 2019). "Most importantly, SBI-756 eradicated BRAF-inhibitor resistant melanoma cells, as well as EIF4EBP null cancer cells, which are resistant to MTOR inhibitors." (PMID 30072418, 2019). "The main target of PTEN phosphatase activity is one of the most significant cell growth and pro-survival signaling pathway in cancer: PI3K/AKT/mTOR." (PMID 31366089, 2019). "In this study, to get a better understanding of the regulation of cytoophidium, we used a human cancer cell line and Drosophila as model systems to investigate the regulation of cytoophidium assembly by mTOR." (PMID 30857853, 2019). "For example, abnormal PI3K-Akt-mTOR signaling is one of the most common dysfunctions present in human cancers (Janku, Yap & Meric-Bernstam, 2018)." (PMID 31660262, 2019). "We also found that PC1 interacts with mTOR and Jak signalling and affects their activity in cancer cells." (PMID 31251475, 2019). "The discovery of rapamycin and the mTOR pathway facilitated the elucidation of how cancer cells reprogram their metabolism in order to acquire nutrients that are necessary for their growth and proliferation." (PMID 31817676, 2019). "Uncontrolled/hyperactivated PI3K/AKT/mTOR signaling leads to dysregulated protein synthesis, which contributes to carcinogenesis and cancer progression." (PMID 31586263, 2019). "While some of the mTOR inhibitors have been approved to treat cancer patients, more mTOR inhibitors are under check to fulfill their promise for cancer therapy." (PMID 31277692, 2019). "While mTOR inhibitor monotherapy has efficacy in some type of cancer, preclinical studies demonstrate strong rationales for combinatorial treatment with mTOR inhibitors and other drugs." (PMID 31277692, 2019). "Consistent with our results, other studies indicated the potency of lncRNAs facilitating the cancer cell growth through mTOR and PI3K signaling pathways, yet reports on BCP-ALL subtypes have been lacking so far." (PMID 30642353, 2019). "Substantial evidence reveals that the potential mechanisms between autophagy and apoptosis including endoplasmic reticulum stress, PI3K/mTOR, and Bcl-2 in cancer cells." (PMID 31817161, 2019). "As cancer cells and activated Th cells use glycolysis and the PI3k/ Akt/mTOR pathway plays a crucial role in both cells, it can be concluded that flavonoids also suppress this pathway in Th cells." (PMID 30766532, 2019). "As expected, mTOR inhibition raises GAS5 levels, although Pickard and Williams (2014) found that both PI3K and mTOR inhibition are needed to elevate GAS5 levels in different cancer cell types in vitro." (PMID 31533355, 2019). "Hyperactivation of the PI3K/AKT/mTOR signaling pathway is found in many types of human cancers, and play key roles in regulating cell growth and tumorigenesis." (PMID 31665029, 2019). "mTOR is a downstream regulator of the PI3K/AKT/mTOR pathway and is a known target for cancer therapy, and mTOR inhibition leads to the blockade of downstream pathways, controls the cell cycle, and ultimately leads to cell cycle arrest." (PMID 32010609, 2019). "The AKT/mTOR axis is a classic signalling pathway in cancers that sustains energy homeostasis through energy production activities, such as the Warburg effect, and blocks catabolic activities, such as autophagy." (PMID 30717751, 2019). "Previous studies have reported that Akt/mTOR signaling pathway played a critical role in various biological processes of cancers, such as proliferation, metastasis and survival." (PMID 30853664, 2019).
cancer (continued). "The PI3K/AKT/mTOR intracellular signalling pathway is crucial in cell cycle regulation and plays a role in the longevity of cancer cells." (PMID 31373300, 2019). "In particular, the mTOR complex stimulates anabolic biosynthesis for cancer cell growth and inhibits autophagy, while AMPK signaling triggers the degradation of macromolecules, including lysosomal autophagic catabolism." (PMID 30483817, 2019). "Although rapamycin and catalytic mTOR inhibitors are already successfully used to prevent the rejection of transplants or treat some types of cancer, many studies are needed to translate experimental results to clinical use for female reproductive diseases." (PMID 31649622, 2019). "PI3K/mTOR signaling pathway is one of the most frequently dysregulated pathways in human cancer and plays a critical role in driving tumor initiation and progression." (PMID 30635656, 2019). "BEZ235, which targets both pan class I PI3K and mTOR, has been reported to inhibit cancer cell growth in vitro and in vivo." (PMID 31234823, 2019). "Although mTOR is considered a promising target for cancer therapy, targeting mTOR using rapamycin has produced limited beneficial effects in patients." (PMID 31530290, 2019). "Combined treatment with the glutaminase inhibitor CB-839 and mTOR inhibitors shows efficacy in overcoming therapeutic resistance to other targeted inhibitors in these different types of cancer." (PMID 31817676, 2019). "A study utilizing public tumor genome sequencing data in 2014 reported that 33 mTOR mutations were found to contribute to the hyperactivation of mTOR signaling in various cancer types." (PMID 30754640, 2019). "In culture models, the pharmacological inhibition of PIKfyve activity largely blocks the pro-proliferative effects of mTOR inhibition, when the growth of various cancer cells is supported by albumin scavenging." (PMID 30967004, 2019). "Although mTOR inhibitors exhibit potent anti-cancer effects in many preclinical models, resistance does occur." (PMID 31277692, 2019). "It has been revealed that one of the key pathways regulating cell growth, the phosphatidylinositol 3-kinase/mechanistic target of rapamycin (PI3K/mTOR) signalling axis, is commonly dysregulated in cancer." (PMID 35582282, 2019). "A previous study demonstrated that p-S6 expression in the activation of the PI3K/AKT/mTOR pathway serves as a potential prognostic biomarker and a predictor of cancers with distant metastasis." (PMID 31756179, 2019). "So far, the mTOR pathway has been extensively studied in relation to cancer and described at the spinal cord level in relation to inflammatory and neuropathic pain, but only a few studies have been performed at the brain level." (PMID 30032425, 2019). "The phosphatidylinositol 3-kinase (PI3K)/AKT/mammalian target of rapamycin (mTOR) signalling pathway is hyperactivated or altered in many cancer types and increases expression of downstream targets contributing to anoikis resistance." (PMID 31198853, 2019). "mTOR is a central regulator of cell metabolism and growth, and is considered as a promising target for cancer therapy." (PMID 32039198, 2019). "The evidence linking activated mTOR-network signaling to human cancer has generated great interest in biomarker profiling and therapeutic targeting." (PMID 30795533, 2019). "The mTOR inhibitor everolimus has emerged as a potential combination therapy drug for the treatment of cancer unresponsive to conventional therapy." (PMID 31703728, 2019). "Data in solid tumors demonstrated that the mTOR signal is dysregulated in almost 30% of cancers and is one of the most frequently affected cascades in human cancers." (PMID 30754640, 2019). "The AKT/mTOR signaling pathway is one of the main growth regulatory pathways in both normal and cancer cells, and it can negatively regulate autophagy." (PMID 31053160, 2019).